GPC5 (glypican 5)
Diseases named in the same sentence as GPC5 in open-access papers (continued):
Sharing a sentence is not in itself a finding about the gene and the disease.
hepatocellular carcinoma (4 papers, 2016 to 2026). A malignant tumor that arises from hepatocytes. "In addition, Gpc3, an ortholog of Gpc5, is reportedly involved in canonical Wnt signaling in hepatocellular carcinoma cells." (PMID 29215008, 2017). "In hepatocellular carcinoma (HCC), GPC5 has been revealed to be a direct target of miR-709, and enforced expression of GPC5 inhibited HCC cell proliferation and invasion." (PMID 35183057, 2022).
multiple sclerosis (4 papers, 2011 to 2022). A progressive autoimmune disorder affecting the central nervous system resulting in demyelination. "We found a CT variant (rs7987675) in GPC5, which is associated with typical response to beta interferon therapy in relapsed multiple sclerosis patients." (PMID 22938532, 2012). "Polymorphisms in GPC5 also appear to be associated with the response of multiple-sclerosis patients to interferon beta therapy, and GPC5 appears to be a risk factor in multiple sclerosis." (PMID 21291537, 2011). "Glypican 5 is a cell surface proteoglycan that has been identified in many different multiple sclerosis genetic studies." (PMID 36517845, 2022). "The chromosomal region of 13q31-32, where GPC5 and GPC6 are located, has been previously identified in a GWAS as showing a significant association with genetic susceptibility of multiple sclerosis (MS)." (PMID 32398079, 2020).
sarcoma (4 papers, 2014 to 2021). A usually aggressive malignant neoplasm of the soft tissue or bone. "Recurring GPC5 (Glypican 5) gain/amplification has been detected in a subset of ECS, mostly in the sarcoma component, and the authors linked the involvement of GPC5 with sarcomatous transformation." (PMID 31324031, 2019). "In particular, glypican-5 (GPC5), which encodes a cell-surface proteoglycan that might be a biomarker for sarcoma, was expressed at high levels in association with transformation." (PMID 25978455, 2015). "GPC5, which is a sarcoma cell marker, was markedly overexpressed at later culture stage in association with transformation of UE6E7T-3 cells." (PMID 25978455, 2015). "Thus, the evidence obtained in this study should facilitate assessment of the functional contribution of GPC5-promoting proliferation in sarcoma, as well as the usefulness of EV as a biomarker for sarcoma." (PMID 33606708, 2021). "Furthermore, GPC5 might be a biomarker for sarcoma of human cells." (PMID 25978455, 2015).
autism (3 papers, 2011 to 2021). Persistent deficits in social interaction and communication and interaction as well as a markedly restricted repertoire of activity and interest as well as repetitive patterns of behavior. "For instance, in a genome-wide study in autism patients to identify novel copy number variations (CNVs), four independent CNVs in the GPC5/GPC6 gene cluster were identified." (PMID 29434536, 2018). "Finally, some members of the HSPG protein family, like GPC4, GPC5 and GPC6 have been linked to neurodevelopmental diseases such as autism, schizophrenia." (PMID 29434536, 2018).
gastric cancer (3 papers, 2022 to 2025). A primary or metastatic malignant neoplasm involving the stomach. "Long noncoding RNA (lncRNA) hox transcript antisense intergenic RNA (HOTAIR) is implicated in the progression of gastric cancer (GC) by promoting the microRNA-217 (miR-217)-glypican-5 (GPC5) axis." (PMID 41356665, 2025). "Our data revealed that only GPC1, GPC4, and GPC5 were expressed in MKN74 gastric cancer cells." (PMID 36181793, 2022).
Alzheimer disease (2 papers, 2011 to 2025). A progressive, neurodegenerative disease characterized by loss of function and death of nerve cells in several areas of the brain leading to loss of cognitive function such as memory and language. "Two genes required for fibrillar tau uptake, B3GALNT1 and B3GNTL1, encode glycosyltransferases, and the cell surface proteoglycan, GPC5, identified in Alzheimer’s disease GWAS, is also required for fibrillar tau entry." (PMID 40790356, 2025).
endometrial carcinoma (2 papers, 2021 to 2025). A malignant tumor arising from the epithelium that lines the cavity of the uterine body. "The functional relevance of Glypican-5 (the gene product of GPC5) in the regulation of differentiation and lineage specification has been substantiated in vitro in endometrial carcinoma cell lines." (PMID 40352786, 2025).
Insulin resistance (2 papers, 2019 to 2020). Increased resistance towards insulin, that is, diminished effectiveness of insulin in reducing blood glucose levels. "Vitamin K epoxide reductase complex, subunit 1-like 1 (VKORC1L1), BTD, GPC1, MOCOS, GPC5, AKR1C4, and NMNAT2 are novel biomarkers for the development of insulin resistance." (PMID 30678306, 2019).
lymph node metastasis (2 papers, 2013 to 2016). "Using IHC methods, high GPC5 expression levels were observed in patients with vascular invasion and regional lymph node metastasis." (PMID 24260047, 2013). "Subsequently, we firstly demonstrated that GPC5 was generally downregulated in NSCLC, negatively correlated with lymph node metastasis and patients' prognosis, as well as suppressing the NSCLC invasion and migration in vitro." (PMID 27806326, 2016).
alcohol use disorders (1 paper, 2011). "GPC5 is thus a strong candidate as a gene involved in ethanol response and the development of alcohol use disorders." (PMID 22384374, 2011). "The convergence of these data provides strong support to the hypothesis that GPC5 is involved in cellular and organismal ethanol response and the etiology of alcohol use disorders in humans." (PMID 22384374, 2011).
Aleutian disease (1 paper, 2024). "From this, we identified several candidate genes contributing to the growth and feed efficiency (ARID1B, APPL1, TOX, and GPC5), reproduction (GRM1, RNASE10, WNT3, WNT3A, and WNT9B), pelt quality (MYO10, and LIMS1), and Aleutian disease tests (IFNGR2, APEX1, UBE3A, and STX11)." (PMID 38167844, 2024).
amyotrophic lateral sclerosis (1 paper, 2023). Amyotrophic lateral sclerosis (ALS) is a neurodegenerative disease characterized by progressive muscular paralysis reflecting degeneration of motor neurons in the primary motor cortex, corticospinal tracts, brainstem and spinal cord. "Interestingly, downregulation of these genes, with the exception of GPC5, has been associated with brain aging in mice, whereas downregulation of EAAT2 can increase excitotoxicity in Huntington’s disease and amyotrophic lateral sclerosis models." (PMID 36602862, 2023).
Arthritis (1 paper, 2011). Inflammation of a joint. "GPC5 expression appears to be reduced in arthritis and GPC5 is located within a quantitative trait locus for arthritis." (PMID 21291537, 2011). "A SNP within GPC5 appears to be significant for parovirus-induced arthritis." (PMID 21291537, 2011).
Ataxia (1 paper, 2011). Ataxia refers to impaired coordination of voluntary muscle movement. "Taken together, these data implicate GPC5 as a candidate QTL that influences ethanol-induced ataxia." (PMID 22384374, 2011).
autoimmune disease (1 paper, 2023). A disorder resulting from loss of function or tissue destruction of an organ or multiple organs, arising from humoral or cellular immune responses of the individual to their own tissue constituents. "These variants have also not yet been previously associated with the age of onset of MS or any other autoimmune diseases; however, rs10492503 in Glypican-5 gene has previously been significantly associated with an earlier age of onset in male MS patients." (PMID 36883100, 2023).
chronic fatigue syndrome (1 paper, 2022). "One of these SNPs—rs16947237, an intronic variant in GPC5—has previously been associated with self-reported chronic fatigue syndrome in a UK Biobank GWAS analysis." (PMID 36517845, 2022).
Cognitive impairment (1 paper, 2023). Abnormal cognition is characterized by deficits in thinking, reasoning, or remembering. "Therefore, the down-regulation of GPC5 in astrocytes may indicate the downregulation of synaptic formation function in the brain, thus causing cognitive impairment." (PMID 37539343, 2023).
diabetic nephropathy (1 paper, 2014). "GPC5 (glypican-5) has been found to be a susceptibility gene common to nephrotic syndrome diseases, such as membranous nephropathy, immunoglobulin A nephropathy and diabetic nephropathy." (PMID 24705288, 2014).
Hepatitis (1 paper, 2021). Inflammation of the liver. "The expression level of GPC-5 was related to the poor prognosis of OS in sex (female), sorafenib treatment, and hepatitis." (PMID 33902495, 2021).
myelomeningocele (1 paper, 2022). Myelomeningocele is the most severe form of spina bifida. "Array-based comparative genomic hybridization of a cohort of 189 Caucasian and Hispanic cases with non-syndromic lumbo-sacral myelomeningocele identified heterozygous deletions of glypican genes GPC5 and GPC6 as a significant risk factor." (PMID 34842271, 2022).
nephrotic syndrome (1 paper, 2020). A collection of symptoms that include severe edema, proteinuria, and hypoalbuminemia; it is indicative of renal dysfunction. "First, to investigate the proper ratio of TPFE to siRNA, we conducted a control experiment to obtain optimal conditions for knockdown Gpc5 in podocyte, the gene previously proved to be associated with nephrotic syndrome and localized in podocytes." (PMID 33273487, 2020).
osteoarthritis (1 paper, 2024). A noninflammatory degenerative joint disease occurring chiefly in older persons, characterized by degeneration of the articular cartilage, hypertrophy of bone at the margins and changes in the synovial membrane. "For this reason, Glypican 5 and Notum could be promising candidates for biomarkers of osteoarthritis." (PMID 38786073, 2024).
primary sclerosing cholangitis (1 paper, 2020). "In addition, the gene region 13q31-32 containing both GPC5 and GPC6 has also previously been associated with the increased risk of primary sclerosing cholangitis (PSC), a chronic liver disease where a strong association has been identified between the SNP GPC6-rs9524260 and disease." (PMID 32398079, 2020).
retinoblastoma (1 paper, 2024). A malignant tumor that originates in the nuclear layer of the retina. "The focal 13q31.3 amplification in 1 retinoblastoma harbored MIR17HG, a microRNA known to activate MYC(N) signaling, and part of GPC5." (PMID 39079981, 2024).
tumor (28 papers, 2007 to 2026). "The GPC5, a target of miR-217, is implicated in tumor progression." (PMID 41356665, 2025). "Furthermore, loss of GPC5 induces tumor growth through Wnt/β-catenin signaling and correlates with poor outcomes in NSCLC." (PMID 40688491, 2025). "Additional tumor suppressors, including GPC5 and PTPRD, also harbored SIR-associated mutations." (PMID 41153425, 2025). "Although we preliminarily verified that this rare GPC5 germline mutation (c.776C>T) hastens LUAD progression, its physiological functions in tumor progression remain contentious." (PMID 40352786, 2025). "Upregulation of GPC5 contrastively suppresses tumor migration, invasion, and proliferation in NSCLC." (PMID 40688491, 2025). "Some miRNAs, such as miR-297, miR-301b, miR-620, and miR-709, promote tumor malignancy by negative regulation of the GPC5-coding gene in cancer." (PMID 40688491, 2025). "In the FFPE tumor sample of patient II-6, immunohistochemistry revealed GPC5 expression showed a slightly reduced expression level of GPC5 in the tumor sample versus normal lung, consistent with previous studies." (PMID 40352786, 2025). "Crucially, siRNA-mediated GPC5 knockdown phenocopied these oncogenic effects, providing definitive evidence of its tumor-suppressive function." (PMID 40352786, 2025). "In this study, we identified a rare germline mutation in GPC5 (c.776C>T) in a LUAD pedigree and examined its effect on the tumor-suppressing functions of GPC5." (PMID 40352786, 2025). "The lower expression of GPC5 is observed in various tumor types, including hepatocellular carcinoma, NSCLC, prostate cancer, and glioma." (PMID 40688491, 2025). "In non-small cell lung cancer, some reports have suggested that GPC5 is a tumor promoter, whereas others insist that it is a tumor suppressor." (PMID 33606708, 2021). "Spearman correlation analysis indicated that the decreased expression of GPC5 mRNA in the tumor was positively correlated with N stage, pTNM stage and differentiation." (PMID 27806326, 2016). "Tumor cells with high levels of GPC5 expression were more invasive compared to those with low levels of GPC5 expression." (PMID 24260047, 2013). "In contrast, GPC5 has also been considered as a tumor suppressor." (PMID 40688491, 2025). "Thus, further investigations are essential to clarify the role of GPC5 as a tumor promoter or suppressor." (PMID 40688491, 2025). "Some reports have described that GPC5 overexpression promotes tumor malignancy." (PMID 40688491, 2025). "Moreover, via binding Wnt3a on the cell surface, GPC5 inhibits Wnt/β-catenin signaling, thereby mediating tumor suppressor action." (PMID 34976811, 2021). "Glypican-5 (GPC5) was a novel tumor metastasis suppressor in LUAD through suppresses EMT." (PMID 33062704, 2020). "However, the mechanism responsible for GPC5-mediated effects on tumor metastasis remain to be clarified." (PMID 24260047, 2013). "We hypothesize that GPC5 may promote tumor cell EMT by facilitating the activation of the Wnt pathway, which subsequently may enhance tumor invasiveness and metastasis, which requires further studies." (PMID 24260047, 2013). "Tumor cells with high GPC5 expression levels exhibited poor differentiation (P=0.04)." (PMID 24260047, 2013). "Genetic analysis revealed the GPC5 c.776C>T variant exhibited complete cosegregation with LUAD phenotype in the pedigree while being absent in control populations (gnomAD frequency: 0.000003989), accompanied by significantly reduced GPC5 expression in tumor tissues." (PMID 40352786, 2025). "Future studies should investigate whether GPC5-mutant LUAD patients exhibit altered tumor-infiltrating lymphocyte profiles and combine other in vivo and in vitro studies to explore the molecular mechanisms, thereby providing more in-depth therapeutic strategies." (PMID 40352786, 2025).
tumor (continued). "It is worth noting that, in this work, we report a decrease in the expression of GPC1 and an increase in GPC5 with increasing tumor grade, suggesting that the involvement of these molecules in cancer, as in the case of GPC3, may range from tumor suppressors to oncogenes depending on tumoral context." (PMID 24570896, 2014). "In addition, we performed ES on the FFPE tumor and identified no “second-hit” GPC5 variants." (PMID 40352786, 2025). "While GPC1 and GPC2 exhibited a strong net upregulation in tumor samples over normal across the board of cancer types, other members like GPC4, GPC5, and GPC6 were characterized by tissue-specific cancer expression patterns." (PMID 36944188, 2023). "Glypican-5 (GPC5) is considered a cancer-related proteoglycan in various cancers, as tumor suppressor." (PMID 34249755, 2021). "The aim of the present study was to investigate the expression pattern of GPC5 in NSCLC cell lines and tumor tissue samples." (PMID 24260047, 2013). "GPC5-mediated activation of several pathways, such as Wnt, hedgehog, and FGF, might be involved in tumor development and progression." (PMID 40688491, 2025). "In total, recurrent (>3) MEI were observed in 329 protein-coding genes of which 28 genes are annotated in the Cancer Gene Consensus with either oncogenic (ALK1, ERBB4, TSHR, PREX2, CTNNA2, CTNND2) or tumour suppression roles (EBF1, LRP1B, PTPRD, GPC5, ROBO2, PTPRT)." (PMID 35301290, 2022). "Tumor-marker genes (HMGA2, TPD52, and GPC5) were overexpressed in U3-C and U3-DT." (PMID 25978455, 2015). "As with SDC2 and GPC5, expression was not influenced by the location of the tumor, suggesting that this is another common feature shared by all neoplasms, wherever they are in the body." (PMID 24570896, 2014). "Our data show GPC5 protein expression to be correlated with tumor grade, increasing in tumors of grade 2 or higher, and with tumor stage, increasing in tumors of stages 3 and 4, but not with patient survival or the topography of the tumor." (PMID 24570896, 2014). "In the present study, we identified GPC5 expression in NSCLC tumor cells and these expression levels may have affected tumor cell migration." (PMID 24260047, 2013). "Moreover, the expressions of GPC-1, GPC-2, GPC-4, GPC-5, and GPC-6 were not significantly different between tumor and normal liver tissues." (PMID 33902495, 2021).